EGFR (epidermal growth factor receptor)
Diseases named in the same sentence as EGFR in open-access papers (continued):
Sharing a sentence is not in itself a finding about the gene and the disease.
lung cancer (continued). "However, the acquired mechanism of EGFR TKI resistance remains unknown for about one-third of EGFR TKI-resistant lung cancer patients." (PMID 35399731, 2022). "On the other hand, PAC1R-mediated EGFR activation may promote the proliferation of certain lung cancer cells by PKC-dependent EGFR activation, and VPAC1 signalling can transactivate EGFR and human epidermal growth factor receptor 2 (HER2) through PKA and Src signalling in breast cancer cells." (PMID 35897648, 2022). "The identification of target gene alterations is an evolution for the lung cancer management, with the combination of tumor genotyping making personalized treatment possible, and it is of great benefit to patients treated with kinase inhibitors (TKIs) for EGFR, ALK, ROS1, BRAF, or MET." (PMID 35600411, 2022). "Based on a cytological study, it was found that morphine could activate the MOR in lung cancer cells, induce phosphorylation of the epidermal growth factor receptor (EGFR), lead to activation of the lower MAPK/ERK/Akt pathway, and promote cell proliferation and invasion." (PMID 35966857, 2022). "Since EGFR, EphA1, and EphA2 positively correlated with Ephexin1 in both colon and lung tissues, we focused on these three proteins and analyzed the survival rates of lung cancer and colorectal cancer patients relative to the expression levels of all four proteins." (PMID 35668076, 2022). "Our study demonstrates that CXCL10 may mediate early NF-κB activation in EGFR-mutant lung cancer." (PMID 36612121, 2022). "Active mutations in the EGFR-tyrosine kinase domain, such as exon 19 deletion and exon 21L858R, are found specifically in lung cancer and are not common in other cancers; for example, the frequency of EGFR mutations in colon cancer is 3% and lung-cancer-specific mutations are rare." (PMID 35681723, 2022). "Therefore, detection of lung-cancer-specific mutant EGFR DNA in BALF along with compatible CT findings suggesting malignancy may be sufficient to diagnose EGFR-mutant lung cancer to guide EGFR-TKI treatment." (PMID 35681723, 2022). "Our study also found that MA, acting as a PLA2 inhibitor, significantly inhibited KRAS expression and the downstream ERK pathway in lung cancer cells, suggesting that MA may inhibit KRAS by suppressing PLA2 and overcome the EGFR-TKI resistance in KRAS- mutated lung cancer cells." (PMID 36712673, 2022). "NSCLC with sensitive epidermal growth factor receptor (EGFR) mutations may be susceptible to treatment with EGFR tyrosine kinase inhibitors (EGFR-TKIs), a breakthrough in lung cancer treatment this century that has opened a new chapter in the targeted therapy of solid tumors." (PMID 36172729, 2022). "This is especially important given the known resistance to immune checkpoint blockade in EGFRMT lung cancers relative to that in NSCLC patients without EGFR mutations and the possibility that targeting MERTK could overcome this immune resistance." (PMID 35708914, 2022). "Moreover, no additional EGFR targeted therapies for certain EGFR gene mutations, which also maintained a relatively high mutation rate among the lung cancer patients in the coal-producing zones was observed." (PMID 35606799, 2022). "As a recent example, driver mutations in ctDNA (EGFR, KRAS, or BRAF) and serum concentrations of Cyfra21-1, and possibly CA125, have been described as relevant useful biomarkers for therapy response monitoring and early detection of progression during therapy in lung cancer." (PMID 35892331, 2022). "Whether advanced lung cancer patients with EGFR mutations can benefit from immunotherapy has not been concluded at present, and more targeted clinical trial data are still needed." (PMID 35831785, 2022). "Researchers found that TNF played a key role in inducing resistance to epidermal growth factor receptor inhibition in lung cancer, and suggested that a concomitant inhibition of epidermal growth factor receptor and TNF maybe a potentially new treatment strategy for lung cancer patients." (PMID 34983358, 2022).
lung cancer (continued). "Because of crosstalk between Src and EGFR, it has been hypothesized that the suppression of Src and its downstream signaling partners may induce apoptosis and overcome gefitinib resistance in lung cancer cells." (PMID 35408854, 2022). "In addition, co-treatment with seribantumab and EGFR-neutralizing antibodies in EGFR mutant-bearing lung cancer cell lines and xenograft models, which became resistant to EGFR inhibitor/neutralizing antibodies, was able to overcome resistance to EGFR-targeted therapy and inhibit tumor growth." (PMID 36293051, 2022). "Furthermore, it has been shown that ferroptosis can be targeted to treat EGFR-mutant lung cancer." (PMID 35359830, 2022). "However, we estimate the proportion of patients with private drug insurance among all EGFR-TKI users to be low since about 70% of lung cancer patients in Quebec are diagnosed at age 65 or older, when 90% of Quebec residents are registered for public drug coverage." (PMID 36354696, 2022). "However, this was different from other studies that EGFR 19del mutant lung cancers had a lower TMB compared with EGFR L858R mutant lung cancers, might be due to, for instance, different races, histology and stages." (PMID 36505399, 2022). "Therefore, ncRNAs encoding tumor-suppressor proteins may serve as a novel therapeutic regimen for EGFR TKI-resistant lung cancer." (PMID 36139582, 2022). "In particular, the EGFR inhibitor gefitinib, whose FDA approval in unselected lung cancer patients was rescinded because of lack of efficacy in post-marketing studies, was re-approved once trials could be done with EGFR mutation-based patient selection." (PMID 36045401, 2022). "Furthermore, STORM revealed PIP2 clustering overlapping with EGFR clustering in membranes of lung cancer cells and normal lung epithelial cells, and EGFR clustering and downstream signaling were reduced after PIP2 depletion or mutation of membrane-proximal EGFR residues." (PMID 35205690, 2022). "Representatively, lung cancer harboring EGFR mutations is generally not considered for treatment with ICIs given that multiple clinical trials have found that ICIs provide limited survival benefit for this particular population, whereas KRAS mutation is a favorable biomarker for ICIs benefit." (PMID 36426352, 2022). "Three EGFR mutations in our study were rare mutations, in contrast to previous studies that reported lower TMB in EGFR-mutant lung cancer compared with EGFR wild-type, we found TMB in EGFR-mutant patients was higher in our study, which might be associated with mutation type and the signature of SHC." (PMID 36741696, 2022). "Clinically measurable factors affecting the progression‐free survival (PFS) of patients receiving osimertinib as first‐line therapy for epidermal growth factor receptor (EGFR) mutation‐positive advanced non‐small cell lung cancer (NSCLC) have not yet been established." (PMID 36082812, 2022). "With this causality and given that 5% of NSCLC tumors have mutations in PTPRH, and an estimated 235,000 cases of lung cancer occurring yearly within the United States, over 10,000 patients who present with PTPRH mutations could potentially benefit from EGFR targeted TKI therapy." (PMID 36054194, 2022). "However, these combination treatment strategies do not reflect individual biological characteristics of lung cancer with EGFR mutations." (PMID 35326664, 2022). "Therefore, targeted interference with SHC1/EGFR interactions may be a new strategy for the lung cancer treatment." (PMID 35706930, 2022). "However, the efficacy and safety of adjuvant EGFR TKI therapy in patients with resected lung cancer is still debated, although prospective randomized controlled trials have shown improved disease-free survival results for adjuvant EGFR TKI use in patients with resected lung cancer." (PMID 35360423, 2022).
lung cancer (continued). "Interestingly, we found that high expression levels of EGFR/MAP2K1/mTOR/TEAD1/YAP1 in lung cancer significantly decreased overall levels of active cytotoxic lymphocytes, mediated dysfunctional T-cell phenotypes, and produced worse overall survival rates of lung cancer cohorts." (PMID 35655775, 2022). "However, recent available evidence indicates that multiple low-dose treatment can be effective: in EGFR-mutant lung cancer, vertical targeting of EGFR signaling pathway with three or four drugs can be effective even when the drugs are used at 20% of the single agent concentration." (PMID 35814399, 2022). "However, another study showed that compared 212 lung cancers without EGFR mutation, outcomes of ICI treatment were worse in patients with EGFR19del but similar in those with EGFR L858R; in contrast, EGFRT790M status did not affect response to ICI treatment." (PMID 35265073, 2022). "However, the importance of EGFR protein expression in other cancers, such as lung carcinomas, remains controversial, as the level of EGFR overexpression may vary anywhere from 25 to 82% in colorectal cancers." (PMID 35455247, 2022). "Interestingly, stable ectopic expression of the wild-type EGFR increases the ERRFI1 mRNA level but not the protein level whereas ectopic expression of the L858R mutant EGFR, which is a common EGFR mutant in lung cancer, elevates both the mRNA and protein levels of Gene 33 in H1299 lung cancer cells." (PMID 34206547, 2021). "It is very important to establish the relationship among gene mutations, treatment, and prognosis, especially for driver or key genes, since this may suggest targets for more effective drugs in clinical practice such as EGFR in lung cancer and KIT in gastrointestinal stromal tumors." (PMID 34368001, 2021). "SPP1 enhanced the second-generation epidermal growth factor receptor (EGFR) tyrosine kinase inhibitor (TKI) resistance in lung cancer, which offered a new scheme for targeted therapy that inhibiting SPP1 might be a therapeutic target to overcome afatinib resistance." (PMID 33968738, 2021). "We hypothesized that EVs may mediate drug sensitivity in heterogeneous lung cancer via the transfer of cargo from EGFR-mutant cells to EGFR wild-type cells, thus contributing to the sensitivity to EGFR-TKIs observed in heterogeneous EGFR-mutant NSCLC." (PMID 33671000, 2021). "Thus, understanding of molecular mechanisms contributing to basal and drug-induced autophagy is paramount for uncovering druggable alterations that may be able to prevent or alleviate resistance to EGFR-TKI in lung cancer patients." (PMID 34359849, 2021). "Hence, the validation of the prognostic value of PD-L1 or EGFR/HER2 immunoexpression in patients with lung cancer requires further studies with a larger sample size to establish their role in identifying the molecular subgroup for the purpose of target therapy and overall survival." (PMID 34367799, 2021). "Moreover, LSM1 was highly correlated with “Chemoresistance pathways mediated by constitutive activation of PI3K pathway and BCL-2 in small cell lung cancer” and “IGF-1 receptor/EGFR cooperation in lung cancer”, which suggested that it also plays an important role in lung cancer tumor growth." (PMID 34638387, 2021). "Oncogenic driver gene mutations, such as those in epidermal growth factor receptor (EGFR), KRAS, ALK, human epidermal growth factor receptor 2 (HER2), and mesenchymal-epithelial transition (MET), play essential roles in the initiation, progression, and clinical treatment of lung cancer." (PMID 34660325, 2021). "Previous studies have shown that PTS inhibits the expression of epidermal growth factor receptor, thereby reducing p-Akt levels, which leads to decreased activation of the G- and S-phases of the cell cycle, ultimately inhibiting the proliferation of lung cancer cells." (PMID 33623100, 2021).
lung cancer (continued). "Also, loss of promyelocytic leukemia protein (PML) isoform IV, a suppressor of transcriptional activity of EGFR, for instance, on cyclin D1 gene promoter in lung cancer cells also contributed to the EGFR-mediated mitochondria-induced apoptosis and cell cycle arrest." (PMID 36046435, 2021). "Unlike RAS-mutated lung cancers, EGFR mutant tumors have a generally low response to immunotherapy." (PMID 34038737, 2021). "Therefore, it is not surprising that each EGFR-mutated lung cancer cell line employs their “preferred” mechanism(s) to achieve drug tolerance." (PMID 34202566, 2021). "Therefore, RESV treatment impacts IL-8 expression only in EGFR-mutant lung cancer cells." (PMID 33652978, 2021). "Therefore, we supposed that the effectiveness of EGFR inhibitors in lung cancer may be improved by methylation modification in their sensitivity genes." (PMID 34356665, 2021). "It has been previously reported that certain genes may be critical in the pathogenesis of systemic sclerosis (chemokine CCL2 and CXCL4) and lung cancer (including EGFR and HER2), but our results are more convincing in terms of reliability and universality owing to the large sample size." (PMID 33691643, 2021). "Furthermore, the inhibitory effects of phenformin on the proliferation of H292 ER cells were significantly decreased by HK2 overexpression, indicating that enhanced glycolysis reduces the anticancer effects of phenformin in lung cancer cells with acquired EGFR-TKI resistance." (PMID 34367462, 2021). "Although specific genes that uniquely control the metabolic status of cancer cells have been successfully elucidated in a few studies, we could not find a common metabolic point for which mitochondrial function is upregulated in three different EGFR-TKI-resistant lung cancer cell lines." (PMID 34367462, 2021). "In addition, some studies found that the aberrant expression and activation of MET result in the activation of the ERBB3/PI3K/AKT pathway, which is associated with the resistance of EGFR inhibitors in lung cancer, and this resistance can be reversed by combining MET inhibitors and EGFR inhibitors." (PMID 34761497, 2021). "Furthermore, there was a smaller proportion than the general prevalence of sensitizing EGFR mutation in this cohort (34.7%) which represented physician selections of preferred non-oncogenic addicted advanced stage lung cancer for anti-angiogenic treatment." (PMID 33996532, 2021). "Therefore, the effect of EGFR inhibitors in lung cancer may be affected by regulating the methylation level of the drug-sensitive gene promoter region." (PMID 34356665, 2021). "Moreover, it may be suggested that SH003 is an effective herbal medical regimen, at least, for EGFR wild-type lung cancer cell lines." (PMID 34445110, 2021). "A multicentre case-control study suggested that environmental tobacco smoke exposure could influence the EGFR mutation profile of lung cancer in never smokers and that exposure during adulthood might reduce the probability of EGFR mutation." (PMID 33889543, 2021). "In a study with 248 lung cancer patients without treatment, researchers found that their model for prediction of EGFR mutations could reach an AUC of 0.87 when combined clinical and radiomic signature." (PMID 33693966, 2021). "Change in expression of such biomarkers could have a profound impact on the choice and efficacy of a selected targeted therapeutic, and hence the objective of this study was to analyze discordance in EGFR status in patients with lung cancer brain metastasis (LCBM)." (PMID 35201504, 2021).
lung cancer (continued). "Interestingly, the first lung tumor, excised in the year 2016, did not contain EGFR mutations, while we confirmed the presence of EGFR mutation (a combination of G719S and L833V substitutions) in the second lung cancer lump." (PMID 33407806, 2021). "This study may fill the gap in lung cancer data analysis on one-specific mutant population, highlights the need for differential analysis of different oncomutations in cancer and also provides clues for the clinical treatment of EGFR-WT NSCLC patients." (PMID 33763356, 2021). "Patients with small cell lung cancer and mutation-rich non–small cell lung cancer (eg, epidermal growth factor receptor, anaplastic lymphoma kinase, ROS-1) could not be separated." (PMID 34342588, 2021). "Thus, future ctDNA plasma testing and identification of PI3K pathway alteration in EGFR-mutant lung cancer patients could classify the patient for a combination treatment of osimertinib and PI3K pathway inhibitor." (PMID 33741979, 2021). "However, EGFR induces tumorigenesis in lung cancer, breast cancer, and glioblastoma." (PMID 34884765, 2021). "Recent work demonstrated that afatinib, an approved irreversible electrophilic covalent EGFR/HER2 inhibitor for lung cancer treatment, increased TRIB2 degradation in human acute myeloid leukemia (AML) cancer cells, demonstrating for the first time that TRIB2 might be a druggable protein." (PMID 34198908, 2021). "Finally, we highlight recent breakthroughs in the use of EGFR TKIs in non-metastatic EGFR-mutated lung cancer." (PMID 34202748, 2021). "One explanation for this is that the co-occurrence of other genomic or epigenomic alterations with DDR mutations may dilute the influence of initial chemotherapy in lung cancer patients with no EGFR or ALK mutations." (PMID 34604048, 2021). "In summary, this study demonstrated the correlation between DNA methylation and the effectiveness of EGFR inhibitors, and suggested that DNA methylation might be one of the important regulatory factors affecting the sensitivity of EGFR inhibitors in lung cancer patients." (PMID 34356665, 2021). "In recent years, clinical studies have shown that immunotherapy (PD-1/L1 monoclonal antibody, CTLA-4 inhibitor) has great potential in the treatment of lung cancer patients without epidermal growth factor receptor (EGFR) and anaplastic lymphoma kinase (ALK) mutations." (PMID 34587898, 2021). "Interestingly, Axl may also be the downstream target of YAP that sustains YAP-driven EGFR-TKI resistance in EGFR-addicted lung cancer cell lines." (PMID 33562150, 2021). "Because the reactivation of OXPHOS in most of the lung cancer cell lines with acquired EGFR-TKI resistance was observed, we hypothesized that phenformin sensitivity could be diminished by the restoration of glycolysis (Warburg effect) in the resistant cell types." (PMID 34367462, 2021). "In addition, the close structural similarity of exon 20 of EGFR and receptor tyrosine-protein kinase erbB-2 (ERBB2) indicates that our findings could be applicable to ERBB2 mutated lung cancer." (PMID 34944068, 2021). "Thus, much like the amplification of EGFR itself, GGA2 may work through increasing active mutant EGFR protein levels in lung cancer cells to promote growth." (PMID 34944063, 2021). "In addition to codrivers in NSCLC, MET mutations are generally thought to be mutually exclusive with mutations in other major lung cancer drivers and have not been shown to be associated with acquired resistance to EGFR-TKI therapy." (PMID 34205733, 2021).